ACE (angiotensin I converting enzyme)
Diseases named in the same sentence as ACE in open-access papers (continued):
Sharing a sentence is not in itself a finding about the gene and the disease.
Hypertension (continued). "Several classes of drugs are currently available to treat hypertension, including angiotensin-converting enzyme (ACE) inhibitors, angiotensin II (Ang II) receptor blockers (ARBs), calcium channel inhibitors, β-blockers, and loop diuretics." (PMID 35269547, 2022). "Some peptides inhibit ACE, and these can help maintain normal blood pressure and prevent escalation of hypertension by subverting the renin-angiotensin-aldosterone system." (PMID 36232463, 2022). "Potent synthetic ACE inhibitors, such as captopril, enalapril, and lisinopril, are widely used as clinical treatments for hypertension in humans." (PMID 36557925, 2022). "Many synthetic ACE inhibitors like captopril, enalapril, benazepril and lisinopril have been widely used in the clinical prevention of hypertension." (PMID 36082025, 2022). "Cilazapril which can be used to treat hypertension and heart failure has similar side effects to other ACE inhibitors." (PMID 36386190, 2022). "Traditional therapeutic schedule is limited by various side effects, and the edible protein-derived peptides have been explored as a potential nutrient to the cardiovascular system because of its anti-hypertension, ACE inhibition, and vasodilation activities." (PMID 36296612, 2022). "Nifedipine, losartan, and enalapril are drugs used ubiquitously for hypertension and belong to the calcium channel blocker, angiotensin II receptor blocker, and angiotensin-converting enzyme (ACE) inhibitor classes, respectively." (PMID 36293505, 2022). "Angiotensin receptor blockers (ARBs) and angiotensin-converting enzyme inhibitors (ACE-Is) are often used to treat hypertension." (PMID 36368916, 2022). "Overactivation of the ACE/Ang-II/AT1R pathway has been associated with several CV pathologies, including hypertension, heart failure, vascular inflammation and remodeling, coagulation, and atherosclerosis." (PMID 35586646, 2022). "Among them, ramipril is an angiotensin-converting enzyme (ACE) inhibitor used in the treatment of hypertension and heart failure." (PMID 35976917, 2022). "ACE inhibitors comprise the first line of medicines employed in hypertension therapy, heart failure, myocardial infarction, and diabetic nephropathy." (PMID 36432059, 2022). "For that reason, RAAS inhibitors, such as direct renin inhibitors, ACE inhibitors, ARBs, and aldosterone antagonists, are often prescribed in the treatment of hypertension." (PMID 36430371, 2022). "Although the dogs received medication (ACE-i) for the control of hypertension, serum AGT concentrations were still high after treatment." (PMID 35203200, 2022). "Captopril was chosen as reference since it is known as a potent, competitive inhibitor of ACE and is thus known to be used in the treatment of hypertension." (PMID 35415680, 2022). "ACE is of paramount importance in the development of hypertension, since ACE is able to convert angiotensin I into angiotensin II (Ang II), a polypeptide with several biological effects in vascular smooth muscle cells." (PMID 35621847, 2022). "Captopril is used for the treatment of heart diseases (hypertension and congestive heart failure), as a competitive inhibitor of ACE (angiotensin I-converting enzyme), by converting the angiotensin I to angiotensin II." (PMID 35621589, 2022). "Notwithstanding, all final protein hydrolysates presented ACE-inhibitory capacity, thus being promising compounds to manage hypertension." (PMID 36294989, 2022). "Enalapril is also an ACE inhibitor, which is also widely used in the treatment of hypertension, with a similar pathomechanism to lisinopril, however, enalapril does not cross the blood–brain barrier." (PMID 36361252, 2022). "Data showing the beneficial effects of ACE inhibitors and ARBs in the treatment of hypertension during the COVID-19 pandemic are rising." (PMID 35075396, 2022).
Hypertension (continued). "Another study conducted by the European Society of Cardiology stated that non-O blood groups have higher angiotensin-converting enzyme (ACE) inhibitor-induced cough activity in patients with hypertension." (PMID 35291516, 2022). "Many studies have been carried out on the synthesis of ACE inhibitors, such as captopril, enalapril, alacepril, and lisinopril, which are used in the treatment of hypertension and heart failure." (PMID 35733526, 2022). "The authors argued that both Ang II infusion and L-NAME treatment upregulated renal ACE 1.5- to 2-fold, thus enhancing local Ang II generation and sodium transporter activation and subsequently leading to hypertension via a reduction in natriuresis." (PMID 35710133, 2022). "Arterial Hypertension (AHT) is ordinarily treated using drugs that inhibit the Angiotensin I-Converting Enzyme (ACE-1; EC 3.4.15.1) such as Enalapril® or Captopril©." (PMID 35741988, 2022). "These RTCs clearly and arguably, lend strong credence to the limitations of ACE inhibitors and ARBs in cardiorenal protection in hypertension, CKD, and heart failure." (PMID 36447726, 2022). "Both lisinopril and enalapril are angiotensin-converting enzyme (ACE) drugs and widely used in the treatment of hypertension." (PMID 36361252, 2022). "In a murine model that RAAS-dependently provokes hypertension as a result of 5/6 nephrectomy, ACE expression was significantly increased in the lungs of wildtype mice and a rise in MK expression in their plasma, lungs and kidneys was detected." (PMID 36204583, 2022). "The most common drugs used to treat hypertension, heart failure, and diabetes mellitus are ACE inhibitors due to their ability to modulate angiotensin II levels, vasoconstriction, and aldosterone and bradykinin secretion." (PMID 36143487, 2022). "The main approaches include: (i) prevention of the conversion of Ang I to Ang II by inhibiting ACE; regulation of systolic and diastolic blood pressure in vivo, leading to a decrease in hypertension." (PMID 36176638, 2022). "The inhibition of enzymes in the RAS pathway, especially ACE, is regarded to be a potent therapeutic approach in the treatment of hypertension, and the most effective drugs to treat hypertension are potent ACE inhibitors." (PMID 36558429, 2022). "Unrelated to CIP transfusion, patients with hypertension or those on an ACE inhibitor had significantly longer time to PCR negativity, which is in keeping with other reports in the literature." (PMID 35196802, 2022). "This trial was cited as evidence to use ARBs over ACE inhibitors for Black people as part of recent international hypertension guidance." (PMID 34508156, 2022). "Yet, mice devoid of renal ACE were resistant to hypertension induced by Ang II infusion or the NO synthase inhibitor NG-nitro-L-arginine methyl ester (L-NAME)." (PMID 35710133, 2022). "ACE inhibitors (ACEi) and angiotensin receptor blockers (ARBs) have been developed to treat hypertension and maintain cardiovascular health." (PMID 36016727, 2022). "Drugs that are appropriate for initial therapy in most patients with hypertension include thiazide-type diuretics, angiotensin-converting enzyme (ACE) inhibitors/angiotensin II receptor blockers (ARBs) and calcium channel blockers." (PMID 35163696, 2022). "Most of the patients in our new-onset hypertension group were dispensed ACE inhibitors, ARBs, and CCBs and half started with monotherapy." (PMID 35201530, 2022). "For Ag-II-induced hypertension, sodium butyrate and aSCFA stimulants that work in tandem with angiotensin-converting enzyme (ACE) inhibitors have proven effective." (PMID 35795187, 2022). "Overall, angiotensin II receptor blockers (ARBs) and angiotensin-converting enzyme (ACE) inhibitors are the recommended treatments for NASH patients with hypertension." (PMID 35877216, 2022). "Slightly more than half of the patients (53.2%) were previously treated with ACE inhibitors or ARBs for hypertension." (PMID 35036003, 2022).
Hypertension (continued). "The receptor, angiotensin-converting enzyme 2 (ACE2), expression is enhanced in patients with diabetes and hypertension who are treated with ACE inhibitors or angiotensin II receptor blockers." (PMID 35053077, 2022). "Captopril, an FDA‐approved angiotensin‐converting enzyme (ACE) inhibitor used for the treatment of hypertension, was selected because it was reported to increase lifespan in both wildtype C. elegans and mutants that extend lifespan." (PMID 36179270, 2022). "In order to treat hypertension effectively, many synthetic ACE inhibitors, including ramipril, enalapril, captopril, and others, have been used via the biochemical pathway that leads to vasodilation." (PMID 35804705, 2022). "The WHO Essential Medicines List includes ACE (angiotensin-converting enzyme) inhibitors, calcium channel blockers, angiotensin receptor blockers, and thiazide diuretics for management of hypertension." (PMID 34775787, 2022). "With respect to gastrointestinal function, ACE inhibition or angiotensin receptor blockades have been reported to counteract intestinal inflammation, colorectal cancer, and hypertension-induced intestinal damage in rodent models." (PMID 35682739, 2022). "One of the most important therapeutic approaches in managing hypertension is the inhibition of the Angiotensin-converting enzyme (ACE), as demonstrated in many clinical trials." (PMID 36140958, 2022). "Angiotensin converting enzyme (ACE) inhibitors have been successful in ameliorating glomerular injury due to their ability to reduce hypertension and thus mediate the multifold effects of Ang II on mesangial cells." (PMID 35918708, 2022). "Diuretics are effective in the reduction of cardiovascular events in patients with hypertension; moreover, they are more effective than β-blockers and ACE inhibitors in reducing stroke." (PMID 37571938, 2022). "Drugs that inhibit the Angiotensin-converting enzyme (ACE) are common for the treatment of hypertension." (PMID 35889895, 2022). "Angiotensin I converting enzyme (ACE) inhibitory peptides from fermented foods exhibit great potential to alleviate hypertension." (PMID 35938113, 2022). "Among these factors, the renin–angiotensin–aldosterone system exerts a controlling function on blood pressure and hypertension via the synthesis of angiotensin II (a potent vasoconstrictor) catalyzed by the angiotensin-converting enzyme (ACE, EC 3.4.15.1)." (PMID 36432059, 2022). "Since the extract inhibits the angiotensin-I converting enzyme (ACE1), it is also used to treat high blood pressure." (PMID 36135026, 2022). "The distribution of II, ID, DD genotypes of the ACE gene was 21.9%, 29.7%, and 48.4% respectively in essential hypertensive patients and to 45.3%, 25.0%, and 29.7% in controls." (PMID 36355860, 2022). "Renin-angiotensin-aldosterone system (RAAS) inhibitors, including ACE inhibitors and ARBs, are among the most commonly prescribed drugs to treat high blood pressure." (PMID 35075396, 2022). "The extract is also used to treat high blood pressure as it inhibits angiotensin I converting enzyme (ACE1)." (PMID 36135026, 2022). "Identification of potential ACE inhibitors from medicinal plants supported the idea of repurposing these medicinal plants against hypertension." (PMID 34834066, 2021). "Angiotensin-converting enzyme (ACE) is one of the inhibitory enzymes isolated from animals for the treatment of hypertension." (PMID 33642800, 2021). "ACE inhibitors (ACE-I) and angiotensin II type 1 receptor blockers (ARBs) are also frequently used as a treatment strategy to treat diabetes and hypertension." (PMID 33563817, 2021). "In another study of patients with systemic hypertension, monotherapy with either the ACE inhibitor enalapril or the MR blocker eplerenone was associated with elevated serum potassium levels." (PMID 33214722, 2021). "Current first-line medications for hypertension include ACE inhibitors, angiotensin receptor blockers (ARBs), beta-blockers, and calcium channel blockers." (PMID 34947975, 2021).
Hypertension (continued). "His past medical history showed type 2 diabetes with microvascular complications (diabetic retinopathy stage II), and hypertension being treated with angiotensin converting enzyme (ACE) inhibitors." (PMID 34143367, 2021). "The other was for treating hypertension using a lisinopril, which is an angiotensin-converting enzyme (ACE) inhibitor." (PMID 34826238, 2021). "In the majority of studies, adult offspring developed hypertension and kidney disease coinciding with increased expression of ACE and AT1R, and ACE activity." (PMID 33669059, 2021). "Recently, ACE inhibitors have been used to treat hypertension with a lower proportion of critical patients and a lower death rate in COVID-19 patients." (PMID 35095487, 2021). "Among patients with ICA, 4/10 were taking a β-blocker and/or ACE inhibitor for pharmacological treatment of arterial hypertension." (PMID 32700287, 2021). "Angiotensin II receptor blockers (ARBs) and angiotensin-converting enzyme inhibitors (ACE-Is) are first-line treatment options for hypertension which have similar indications and safety profiles." (PMID 33573702, 2021). "Today, ACE inhibitors are the preferred first-line therapy for hypertension (for example, synthetic ACE inhibitor—Captopril), and interest in them continues to increase." (PMID 34375367, 2021). "Note that according Lei Fang9, diabetic patients with arterial hypertension treated with ACE inhibitors and angiotensin II type 1 receptor blockers have an increased expression of ACE that expose more to COVID-19." (PMID 35222572, 2021). "More importantly, the RGE nanoemulsion at the dose of 360 mg/200 g b/w can reduce blood pressure in UUO-induced hypertension rats because they induce a 10.80% decrease in the level of ACE." (PMID 33642802, 2021). "ACE catalyzes the conversion of Ang I into Ang II; the Ang II is a vasoconstrictor that induces oxidative stress and hypertension." (PMID 33442728, 2021). "Imbalance in the ACE/ACE2 pathway results in hypertension, atherosclerosis, thrombosis, heart or kidney failure, and severe respiratory distress, the comorbidities observed among COVID-19 positive patients." (PMID 33632295, 2021). "Like ACE inhibitors, they are often used for treating hypertension and heart failure in older adults." (PMID 34553120, 2021). "Angiotensin converting enzyme (ACE) generates the vasoactive Ang II from the inactive precursor Ang I, and hence, ACE inhibitors are effective and widely used for the treatment of hypertension and kidney diseases." (PMID 34481475, 2021). "Currently, a large numbers of effective and specific ACE inhibitors, including some bioactive peptides derived from food, are used for the treatments of hypertension." (PMID 33800877, 2021). "In this regard, ACE inhibition plays an important role in regulating blood pressure, which explains a worldwide pharmacotherapeutic choice in the management of hypertension and other cardiovascular diseases." (PMID 33886808, 2021). "Factors that were considered to affect LVM, including age, gender, duration of hypertension, use of ACE inhibitors or angiotensin II receptor blockers, BMI, body surface area (BSA), and eGFR were not statistically different between TT and MT carriers." (PMID 33681303, 2021). "First-line medications used in the treatment of hypertension include diuretics, ACE inhibitors or ARBs, beta-blockers, and CCBs." (PMID 34963839, 2021). "ACE is an important enzyme in the renin-angiotensin system, and it is the target gene of ACE inhibitors, a common hypertension medication." (PMID 33541420, 2021). "The patient’s BMI is 41 and has hypertension for which he takes ACE inhibitors and calcium channel blockers." (PMID 33882969, 2021). "Of drug classes commonly used to treat hypertension, ACE inhibitors and angiotensin II receptor antagonists were associated with reduced risk of COVID-19." (PMID 33612113, 2021).
Hypertension (continued). "In a study by Aviram and Dornfield, PJ consumption (50 ml for 2 weeks) in 10 hypertensive patients reduced serum angiotensin-converting enzyme (ACE) levels (by 36%) and SBP (by 5%) which were attributed to antioxidative activity of pomegranate." (PMID 34796029, 2021). "Another most used drug for treating hypertension, Fosinopril, strongly binds ACE with an S-score of −18.9225 kcal·mol-1." (PMID 34351937, 2021). "ACE inhibitors are employed in conditions such as hypertension, heart failure, and diabetes due to their ability to reduce angiotensin II levels, vasoconstriction, aldosterone secretion, and bradykinin." (PMID 33920763, 2021). "This study aimed at evaluating the effect of RG-extract (RGE) nanoemulsion on UUO-induced hypertension and angiotensin-converting enzyme (ACE) production in rats." (PMID 33642802, 2021). "We studied the role of clinical factors in inducing left ventricular regression primary hypertension patients receiving ACE inhibitor/ ARB based regimen." (PMID 35261921, 2021). "Rice bran is rich in albumin hydrolases, which are potent for combating hypertension, diabetes, and oxidation in cells through antioxidant and α-glucosidase, as well as angiotensin-converting enzyme (ACE)-inhibitory activities." (PMID 33810450, 2021). "Despite varying definitions, a threshold of early-onset hypertension is at the age of fewer than 55 years old when recommending first-line medications, such as ACE inhibitors." (PMID 34947975, 2021). "Through univariate logistic regression analysis, four variables were associated with any stage of AKI (P < 0.2) (< 65 years of age, hypertension, higher minimum serum potassium level, and treatment with ACE inhibitors/ARB)." (PMID 34193064, 2021). "There are also studies that showed the effects of EC and TX, respectively, on the RAS or ACE in vivo in conditions of experimental hypertension, which are mentioned below." (PMID 33809620, 2021). "An important question is the place of treatment for hypertension targeting the ACE, including ACE-inhibitors of Angiotensin receptor blockers." (PMID 34513868, 2021). "In spontaneously hypertensive rats (SHR), ACE inhibition during gestation is able to reprogram the development of hypertension and LVH in the offspring, leading to an attenuated form of the disease." (PMID 35366262, 2021). "The results showed a significantly low mean Ishak fibrosis score in patients included in the Group 1 who received ACE inhibitors and ARBs compared to the patients in Group 2 who were treated with other treatments for hypertension." (PMID 33670126, 2021). "This drug was chosen as a positive control since ACE inhibitors are the first line of treatment in hypertension and cardiac failure and it also possesses antioxidant activity." (PMID 34925007, 2021). "In such conditions, in addition to precise control of blood sugar, the main treatment is to reduce RAS activity by ACE inhibitors or ARBs, use diuretics, and limit salt and protein intake to prevent hypertension and albuminuria." (PMID 34289001, 2021). "Since the extract inhibits angiotensin I-converting enzyme (ACE1), it can also be used for the treatment of hypertension." (PMID 33808823, 2021). "Arterial hypertension, cardiovascular diseases, and medication with immunosuppressants, ACE-inhibitors or sartans were more common among SWICOS participants." (PMID 33921459, 2021). "From the perspective of clinical practice, our findings, together with previous RCTs, add support to guidelines recommending the use of ACE inhibitors or ACE inhibitor plus CCB in people with hypertension and kidney dysfunction." (PMID 33766008, 2021). "On the other hand, some hypertension drugs, such as ACE inhibitors (angiotensin-converting enzyme inhibitors) or beta-blockers show an inverse relationship with VLS." (PMID 34281089, 2021). "Both thiazide diuretics and angiotensin converting enzyme (ACE) inhibitors are useful in the management of hypertension." (PMID 35295464, 2021).